TLR9 (toll like receptor 9)
Diseases named in the same sentence as TLR9 in open-access papers (continued):
Sharing a sentence is not in itself a finding about the gene and the disease.
tumor (continued). "Few investigations have been reported about the relationship between TLR9 polymorphisms and the tumor susceptivity." (PMID 22309608, 2012). "In fact, numerous reports have pointed out that a high TLR9 expression is linked to tumor expansion and metastasis, establishing its identification as a new prognostic biomarker in the context of hematological cancer, although its role in prognosis stratification is not still fully established." (PMID 40922674, 2025). "CpG, a well-known TLR9 agonist, enhances antitumor immunity by stimulating DCs to secrete pro-inflammatory cytokines, driving effective T cell responses, and facilitating the recognition of tumor-associated antigens." (PMID 40291558, 2025). "Tumor-derived DNA stimulates dendritic cells in a TLR9-dependent manner, causing them to proliferate, take up antigens, mature within the tumor, and subsequently migrate to the draining lymph nodes to prime tumor-specific CTLs, indicating an essential role of TLR9 in anti-tumor immunity." (PMID 38850110, 2024). "Our findings indicate that TLR9 rs187084 could be a significant prognostic biomarker of worse prognosis and demonstrate its association with lymph node metastases, advanced tumor stage, and poor survival of HPV-negative OSCC patients." (PMID 38850110, 2024). "However, activation of TLR2 and TLR9 in microglia has been shown to be associated with increased levels of pro-inflammatory signals, phagocytic activity, and suppressed tumor growth." (PMID 38893093, 2024). "The variant CC genotype of the TLR9 rs187084 polymorphism might be a marker of poor survival and tumor progression in OSCC." (PMID 38850110, 2024). "DRP1-mediated mitochondrial fission increased cytosolic mtDNA stress and further enhanced chemokine (C–C motif) ligand 2 secretion from HCC cells by the TLR9-NF-κB signaling pathway, which might result in tumor-associated macrophage-mediated tumor growth." (PMID 37525297, 2023). "Therefore, in this study, the synergistic effects of STING and TLR9 agonists and the immunological mechanisms underlying tumor regression and CAFs’ infiltration of the TME were studied in a preclinical colorectal tumor model." (PMID 37901237, 2023). "TLR9 expression was positively linked with sensitivity to the majority of inhibitors, implying that patients with high TLR9 expression may be more susceptible to anti-tumour treatment." (PMID 35801728, 2022). "Because TLR9 is an endosomally localized receptor that is activated by double-stranded DNA, this is a good candidate for mediating cellular responses to the mtDNA associated with tumor cell EVs." (PMID 34623384, 2021). "Moreover, CMP-001, a CpG DNA TLR9 agonist, was reported to have the ability to activate tumor-associated plasmacytoid dendritic cells to produce interferon, which in turn induces antitumor systemic immunity." (PMID 34858419, 2021). "Importantly, Samer et al20 discovered that in liver metastases, NETs promoted tumour growth through activation of TLR9 pathway, and MC38 cells deficient in TLR9 remarkably decreased tumour growth in colorectal liver metastasis mice." (PMID 31821687, 2020). "On the basis of these results, we may suppose that in NPC tumor cells, the presence of the TLR9-1237C allele can help tumor cells to escape apoptosis and enhance tumor growth." (PMID 31886298, 2019). "In addition, the innate immune response‐associated genes, including Oas1a, Oas2, Oas3, Ifi202b, Irf7, and Tlr9, were all down‐regulated, indicating a deficiency in anti‐tumor immune response." (PMID 31602788, 2019). "The microarray data revealed 728 distinctly regulated genes between two populations and the top highly expressed genes (IL2RB, GZMA, GZMB, EMR4, PRF1, CX3CR1, STAT1, and TLR9) in lung-derived Ly6C+ cells from EMT6 tumor-bearing mice are associated with effector T-cell function." (PMID 30926774, 2019).
tumor (continued). "Taken together, these results again underline the importance of BAD-LAMP expression in controlling TLR9 signalling and suggest that its reinforced expression in tumour-associated pDCs contributes to their immunomodulatory phenotypes by decreasing the type-I IFN production capacity." (PMID 29030552, 2017). "More specifically, we hypothesize that the tumor TLR9-dependent, post-treatment weight loss is actually a surrogate marker for self-DNA-induced and TLR9-mediated inflammation that takes place at the tumor site." (PMID 25101078, 2014). "A significant association between TLR3 or TLR9 expression score and tumor stage was also found." (PMID 21129170, 2010). "However, tumours with high TLR9 expression by fibroblast-like cells were associated with low probability of metastasis." (PMID 21129170, 2010). "Therefore, we propose the hypothesis that, in NPC tumor cells, the presence of the mutated allele is associated with higher TLR9 mRNA expression levels." (PMID 31886298, 2019). "Thus, the prognostic significance of TLR9 expression in RCC may be associated with immune responses to the tumour cells." (PMID 21929816, 2011). "One tumor in each mouse was treated with partial Cryo, systemic dual CPI (anti-PD-1 and anti-CTLA-4), intratumoral TLR9 agonist CpG, or combinations thereof, while the second tumor was untreated." (PMID 41677856, 2026). "In situ immunization with vidutolimod (Vidu), a virus-like particle containing a CpG-A TLR9 agonist, has demonstrated antitumor activity in preclinical and early-phase clinical studies; however its effect on tumor-specific CD8+ T cells remain poorly defined." (PMID 41960903, 2026). "YbNano functions as a dual activator of cGAS/STING and TLR9, orchestrating dendritic cell activation and amplifying downstream innate and adaptive immune responses in tumor microenvironment." (PMID 41851580, 2026). "Toll-like receptors (TLRs), including TLR2, TLR4, TLR7, TLR8, and TLR9, are critical pattern recognition receptors on TAMs, with diverse ligands such as tumor proteins, acute-phase proteins, drugs, and bacterial metabolites." (PMID 40948759, 2025). "Preclinical studies have demonstrated that activation of plasmacytoid dendritic cells expressing TLR9 by SD-101 potentiates T cell infiltration into the tumor microenvironment, thereby increasing tumor cell destruction." (PMID 39305392, 2025). "TLR9 promotes tumor growth and increases chemoresistance by recognizing the specific domain of mtDNA, whereas activated NLRP3 triggers downstream signaling cascades and assembles inflammasomes via potassium ion efflux." (PMID 41246345, 2025). "NET formation by vital NETosis boosts HMGB1 production in tumor cells, activating TLR9-dependent pathways and the TLR4/9-COX2 pathway, which improve tumor cell survival and invasion." (PMID 40655142, 2025). "By co‐delivering tumor‐specific neoantigens and a cholesterol‐coupled toll‐like receptor 9 (TLR9) agonist within LNP‐vaxD18, an approximately 60‐fold increase in dendritic cell uptake compared to neoantigen‐adjuvant mixtures is achieved." (PMID 40125791, 2025). "For instance, the drug HAP-ODN, a TLR9 agonist encapsulated by nanomaterials, exhibited significant variability in antitumor efficacy across different tumor-bearing mouse models and even among individuals within the same model." (PMID 41488647, 2025). "The rationale is that activating liver-resident dendritic cells and macrophages via TLR9 will promote tumor antigen presentation and T-cell recruitment." (PMID 40227782, 2025). "ROS-Gels respond to the postoperative tumor microenvironment, continuously releasing drugs to inhibit TLR9/CA9 and block the tumor-hypoxia vicious cycle." (PMID 41142962, 2025). "Sorafenib alone inhibited tumor progression in wild-type (Tlr9+/+) mice and E6446 (TLR9 inhibitor) significantly enhanced the therapeutic effect of sorafenib." (PMID 40038250, 2025).
tumor (continued). "For example, various studies have shown that TLR9 activation can enhance invasion and metastasis by increasing the expression of matrix metalloproteinases in tumor cells, while also supporting the angiogenesis process by increasing VEGF production." (PMID 41155822, 2025). "Although intratumoral injection of Toll-like receptor 9 (TLR9) agonists was shown to improve the efficacy of ICIs by increasing the number of tumor-infiltrating lymphocytes (TILs), it has limited effects on metastatic or deep-seated tumors." (PMID 41291120, 2025). "DRP1‐mediated mitochondrial fission presented in HCC promotes tumour‐associated macrophage infiltration by triggering intracellular mtDNA stress and increasing CCL2 release through the TLR9‐dependent NF‐κB signalling pathway." (PMID 40462487, 2025). "Preliminary results from a study combining TLR9 agonist SD-101 with pembrolizumab showed increased chemokine levels and tumor responses, indicating partially overcome tolerance with manageable hepatotoxicity." (PMID 40227782, 2025). "CpG oligodeoxynucleotides (ODNs), which modulate TLR-4-related pathways to some extent despite being TLR-9 agonists, are being explored for their potential to enhance the anti-tumor immune response." (PMID 40404908, 2025). "Combination approaches, for example BMS-986178 with TLR9 agonist SD-101 and low-dose radiation, aim to further amplify anti-tumor responses." (PMID 41221277, 2025). "TLR9 recognizes specific structural domains, supports tumor growth, enhances chemotherapy resistance, and contributes to the regulation of immune cell function." (PMID 41246345, 2025). "One such strategy involves the use of VMSNs co-loaded with tumor antigens and toll-like receptor 9 (TLR9) agonists." (PMID 40869241, 2025). "Further, we found that the expression of TLR9 was markedly up-regulated in tumor tissues from HCC patients." (PMID 40038250, 2025). "Co‐delivering neoantigens and a TLR9 agonist significantly improve DC activation, tumor immunity, and survival in liver and colorectal cancer models, demonstrating the importance of dual‐site APC targeting for cancer immunotherapy." (PMID 40125791, 2025). "TLR9 agonists are employed as adjuvants in tumor vaccines, and studies have shown that TLR9 agonists can induce antigen-specific memory CD8+ T cells through dendritic cell activation." (PMID 41291120, 2025). "It has been reported that cfDNA can activate TLR9 signaling, for instance, promoting autophagy and tumor growth." (PMID 40226589, 2025). "For instance, in brain cancers like glioma, activation of TLR2, TLR4, and TLR9 promotes tumor growth and metastasis by modulating signaling pathways such as NF‐κB and MAPK." (PMID 40922674, 2025). "Immunofluorescence co-localization analysis showed that TLR9 was co-localized with CD163+ macrophages in tumor tissues from HCC patients." (PMID 40038250, 2025). "Genetic ablation of TLR2, TLR4, and TLR9 in K‐ras‐driven lung adenocarcinoma leads to a reduction of tumor burden, angiogenesis, and tumor cell proliferation." (PMID 40727252, 2025). "TLR9 supports tumor cell growth and chemoresistance by recognizing the CpG structural domain of mtDNA which activates downstream MAPK and NF-κB signaling to promote the associated inflammatory responses." (PMID 41246345, 2025). "In lung cancer, silencing TLR2, TLR4, and TLR9, along with epithelial-specific MyD88/NF-κB signaling, significantly reduces the expression of pro-tumor immunosuppressive factors like RETNLB, while enhancing the expression of anti-tumor cytokines like IFN-γ." (PMID 41200171, 2025). "Subsequent advancements in this formulation were achieved by incorporating two distinct adjuvants (i.e., TLR4 and TLR9 agonists) and protein antigens, resulting in robust anti-tumor efficacy in multiple murine tumor models." (PMID 40507963, 2025). "These EVs transferred invasive properties to recipient tumor cells by activating TLR-9, enhancing endosomal trafficking of pro-invasive receptors." (PMID 40103824, 2025).
tumor (continued). "Disruption of NETs formation, including blocking the IL-8-CXCR2 axis or inhibiting TLR9, can delay tumor progression." (PMID 41019086, 2025). "Mechanistically, NETs release high-mobility group box 1 (HMGB1), which activates TLR9 signaling in tumor cells, promoting their proliferation and metastatic competency." (PMID 40995363, 2025). "The activation of TLR-2 and TLR-9 by PCa cells appears to promote tumour growth; conversely, the activation of TLR-3, TLR-5, and TLR-7 has been suggested as a potential way to prevent PCa." (PMID 39201739, 2024). "The study demonstrated significantly higher TLR-9 expression in the most aggressive PCa, those with the highest the GS, compared to tumours with a more favorable prognosis." (PMID 39201739, 2024). "Unlike immune checkpoint inhibitors that aim to reverse the exhaustion state of T cells, the TLR9 agonist CpG combined with RT draws CD8+ T cells expressing markers associated with activation and proliferation into the tumor." (PMID 39133651, 2024). "These trials reflect a common issue that while TLR9 agonists can induce intratumoral inflammatory responses, their efficacy remains suboptimal, potentially due to insufficient presentation of tumor antigens." (PMID 39772003, 2024). "Agonists for TLRs (TLR3, TLR4, TLR7/8, and TLR9) have been investigated in clinical trials as agents for tumor therapy." (PMID 39516356, 2024). "Our results highlight the need to better understand the cellular and subcellular localization of TLR9 in both normal and tumor breast tissue." (PMID 39123407, 2024). "Targeting STAT3 can improve the efficacy of TLR9 agonist-based immunotherapy, being a checkpoint or the ‘brake’ for anti-tumor immune responses." (PMID 38245798, 2024). "Combining Toll-like receptor 9 (TLR9) stimulation with OX40 antibody activates systemic anti-tumor effects." (PMID 39534532, 2024). "DAMPs released into the tumour microenvironment after radiation therapy trigger TLR9 activation in myeloid cells, promoting angiogenesis and tumour recurrence." (PMID 39704565, 2024). "We aimed to address two possible mechanisms to explain our observations: the stimulation of TLR9 in immune cells to promote antitumor immunity capable of suppressing tumor development, or the TLR9-dependent cell death or direct growth inhibition of RM1 cells." (PMID 38201300, 2024). "The TLR9 agonist IMO-2125 can cause anti-tumor macrophages proliferation and tumor regression in mouse models, as assessed in the clinical study of metastatic melanoma." (PMID 39065562, 2024). "Our study, therefore, provides a possible alternative avenue to boost antitumor IFNs via immune-cell secretion upon TLR9 stimulation, further supporting an antitumor role that TLR9 exhibits in establishing a tumor-suppressive microenvironment." (PMID 38201300, 2024). "After TLR9 agonist stimulation, NK cells were enriched and incorporated into assays to assess their ability to kill tumor cell line targets." (PMID 38918496, 2024). "Using the METTL3 inhibitor STM2457 inhibits TLR9-induced B cell proliferation and immunoglobulin secretion, and opposes TLR9-induced immune responses to assist tumor cell immune escape." (PMID 38537697, 2024). "CpG oligodeoxynucleotides (CpG ODN) offer immunostimulatory agents that elevate the penetration of immune cells into tumor microenvironments (TEM) by attaching to Toll-like receptor 9 (TLR-9) in the endosome." (PMID 38951806, 2024). "This review systematically analyzes studies investigating TLR9 expression in normal and tumor breast tissue." (PMID 39123407, 2024). "The dual-adjuvant effect of liposomes loaded with TLR9 and other immune stimulants has shown significant potential in regressing tumor development and enhancing Th1 immune responses in clinical settings." (PMID 38732254, 2024).
tumor (continued). "The activation of TLR9 in GBM seems to promote hypoxia-induced tumour cell invasion, probably due to the CpG-ODN effect and the activation of MMP-2, MMP-9 and collagenase 3 (MMP-13), as shown in U373 and U87 cell lines." (PMID 38247816, 2024). "A recent study reveals that EBV EBNA1 promotes the degradation of the METTL3 protein via the K48-linked ubiquitin pathway, decreasing TLR9 m6A modification and YTHDF1-enhanced translation, thus promoting tumor immune evasion." (PMID 39695216, 2024). "This design aims to kill tumor cells through SDT while activating toll-like receptor 9 with CpG, further activating DCs and T cells to enhance the anti-tumor immune response." (PMID 38607182, 2024). "TLR9 plays a complex role in breast cancer, acting both as a protector and a promoter of tumor development." (PMID 39123407, 2024). "Recent research has shown that systemic administration of CPG-C, a toll-like receptor 9 agonist, combats brain metastases by activating microglia, which play a pivotal role in tumor suppression and phagocytosis upon direct tumor interaction." (PMID 38229178, 2024). "Understanding the dual role of TLR9 in breast cancer—both as a guardian against tumor cells and as a facilitator of tumor progression—is crucial." (PMID 39123407, 2024). "EBNA1 facilitates the degradation of the METTL3 protein via the K48-linked ubiquitin pathway, reducing TLR9 m6A modification and YTHDF1-enhanced translation, thus promoting tumor immune evasion." (PMID 39695216, 2024). "In vertebrates, the interaction between HMGB3 and TLR3, TLR7, and TLR9, which occurs on the membrane, leads to upregulation of the production of ROS and activation of NF-kB signaling, which ultimately regulates tumor growth and metastasis." (PMID 39062899, 2024). "This study combined TLR9 antagonist (CpG) and HT doxorubicin (Dox) encapsulation within liposomes and increased tumor antigen cross-presentation even at distant tumor sites." (PMID 38543305, 2024). "Elevated expression of TLR2 and TLR9 are correlated with tumor grade and poor survival rates in gastric cancer patients and glioma patients, separately." (PMID 38245798, 2024). "On one hand, TLR9 can combat breast cancer cells by recognizing DAMPs and triggering type 1 immune responses to eliminate tumor cells." (PMID 39123407, 2024). "The identification of the endogenous TLR ligands (i.e. nucleic acids released from dying cells) would clarify the mechanisms for tumor cell growth and potential off-target effects of TLR9 agonist administration." (PMID 39020402, 2024). "Elevated TLR9 expression can enhance the inflammatory response within the tumor microenvironment, promoting tumor growth and progression." (PMID 39123407, 2024). "For example, the activation of TLR7 and TLR9 in stromal cells or transformed epithelial cells can promote tumor progression." (PMID 38390872, 2024). "In summary, TLR9 is emerging as a crucial determinant of breast cancer clinicopathological characteristics, including tumor aggressiveness, response to treatment, and immune evasion." (PMID 39123407, 2024). "TLR9 is also expressed in tumour epithelial and stromal cells across different cancer types, and synthetic TLR9 ligands can stimulate invasion." (PMID 39704565, 2024). "They observed significant tumor burden reduction not only at the TLR9 agonist injection site but also at distant tumor sites." (PMID 39133651, 2024). "The local treatment combining TLR9 agonist with OX40 antibody activates systemic anti-tumor effects." (PMID 39534532, 2024). "The role of TLR9 in cancer development remains controversial, with antitumor and pro-tumor characteristics reported in the literature." (PMID 39123407, 2024). "In a neuroblastoma co-culture system, the TLR9-activated pDCs induced the activation of TRAIL+ NK cells that ultimately killed tumor cells." (PMID 39020402, 2024).